INS (insulin)
Diseases named in the same sentence as INS in open-access papers (continued):
Sharing a sentence is not in itself a finding about the gene and the disease.
metabolic syndrome (continued). "TZDs, on-the-other-hand, are insulin-sensitizing reagents frequently used in the treatment of T2DM and Metabolic Syndrome." (PMID 19284563, 2009). "Secondary research goals include examining changes in components of the metabolic syndrome, inflammatory markers, low-density lipoprotein (LDL-C) cholesterol levels, insulin levels, and glycosolated hemoglobin (HbA1c)." (PMID 20042092, 2009). "Thus, it seemed possible that use of the TG/HDL-C ratio, based on commonly available and standardized measurements, could help clinicians identify persons who were not only insulin resistant but also displayed the characteristic dyslipidemia of people with this defect in insulin action." (PMID 18307789, 2008). "Thus, it may be suggested that postprandial triglycerides and/or insulin and sCAMs are reasonable markers for early metabolic abnormalities and endothelial activation leading to the metabolic syndrome and atherosclerosis, however further studies are needed to confirm this." (PMID 18761738, 2008). "The ability of TZDs such as rosiglitazone and pioglitazone toenhance insulin sensitivity makes them attractive agents for usein the treatment of T2DM and the metabolic syndrome." (PMID 17389771, 2007). "Surplus metabolic syndrome (IDF-, NCEP-, ACE-defined) cases had slightly, but significantly lower BMI, waist circumference, insulin, HOMA-IR and TG values than subjects identified by an insulin measurement requiring definition (WHO or EGIR)." (PMID 18088443, 2007). "Subjects with IDF-defined surplus metabolic syndrome had slightly but significantly lower BMI, waist circumference, diastolic blood pressure, insulin, HOMA and triglyceride values than subjects with WHO-defined metabolic syndrome." (PMID 18088443, 2007). "However, our association analysis of metabolic syndrome quantitative traits supports the hypothesis of a possible influence of PTPN1 genetic variation on insulin sensitivity, plasma lipid levels and hypertension which are characteristics of the metabolic syndrome." (PMID 16677372, 2006). "Mixed-effects models were used to examine glucose and insulin trajectories over time, including sex-by-time interactions, and to adjust for body mass index standard deviation score (BMI_SDS), pubertal stage (Tanner), metabolic syndrome (MetS), and body composition (resistance index)." (PMID 42122980, 2026). "In contrast, individuals with metabolic syndrome showed no statistically significant seasonal changes, although decreases in insulin and HOMA-IR were observed." (PMID 40863890, 2025). "Abnormal Hoxc4 expression in fat is sufficient to modulate metabolic function in mice and humans, while Inpp4b-KO males (but not females) have marked metabolic syndrome with higher adipose levels, insulin resistance, and inflammation in the adipose tissue." (PMID 40161793, 2025). "As a result, targeting insulin actions, particularly in the hypothalamus, seems to be a viable therapeutic method for treating obesity-related disorders, such as irregularities in hunger phenomena, increased HGP, and dyslipidemia." (PMID 40141412, 2025). "Nevertheless, among the obese individuals, there clearly exists a subgroup that maintains long-term normal insulin sensitivity and does not appear to develop any component of the metabolic syndrome." (PMID 37961647, 2025). "Although POP-ABC participants were enrolled with normoglycemia, participants with metabolic syndrome had higher baseline mean FPG and 2hrPG values and lower insulin sensitivity (Si-clamp) compared with those without metabolic syndrome." (PMID 41163811, 2025). "Considering AMPK’s pivotal function in energy metabolism, insulin sensitivity, and hepatic lipid regulation, CRT may offer multifaceted benefits for metabolic syndrome." (PMID 40894211, 2025).
metabolic syndrome (continued). "Patients with dyslipidemia (Class2) had older age (OR [95 % CI]: 1.45 [1.02,2.08), higher HDL (OR [95 % CI]: 2.95 [1.67,5.21]), lower LDL (OR [95 % CI]: 0.71 [0.59,0.87]), and were more likely to be treated with insulin (OR [95 % CI]: 0.23 [0.08,0.63])." (PMID 40084007, 2025). "TG/Glucose and TG/HDL were strongly correlated but retained as they represent complementary aspects of metabolic dysfunction—TG/Glucose reflecting insulin resistance and TG/HDL indicating atherogenic dyslipidemia—providing a broader view of metabolic alterations across BMI categories." (PMID 41302334, 2025). "In the same context, the difference in insulin resistance to CVD was relatively greater in patients without dyslipidemia, which accounted for a large proportion of those with CVD risk because the underlying risk was lower than in those with dyslipidemia." (PMID 40218093, 2025). "Other factors that deteriorate functional capacity include insulin resistance, metabolic syndrome, and lack of exercise." (PMID 41440545, 2025). "Short‐term reduction of FFA concentration does not improve insulin‐stimulated vasodilation in patients with metabolic syndrome." (PMID 39888728, 2025). "Approximately 10% of patients deemed to have MHO exhibit no tenets of metabolic syndrome and an even lower figure (5%) is estimated for those having normal insulin sensitivity at HOMA‐IR as well." (PMID 40371883, 2025). "Rather than presenting with a cohesive metabolic syndrome pattern, patients exhibited diverse combinations of advanced renal disease, variable insulin resistance, and uneven hepatic fibrosis." (PMID 41464315, 2025). "Participants were normoglycemic and normoinsulinemic (mean fasting glucose: 4.8 ± 0.1 mM; mean fasting insulin 10.6 ± 1.6 mIU/L), and showed no signs of dyslipidemia (mean total cholesterol: 4.2 ± 0.2 mM; mean triglycerides: 0.8 ± 0.1 mM)." (PMID 39797666, 2025). "While robotic platforms are increasingly used in metabolic surgery, clinical outcomes of sympathectomy (surgical or endovascular) have shown promising effects in controlling glucose, insulin sensitivity and in reducing sympathetic overactivity in patients with T2DM or metabolic syndrome." (PMID 41446325, 2025). "The participants with metabolic syndrome had significantly lower insulin sensitivity and numerically higher insulin secretion compared with participants who did not meet the criteria for metabolic syndrome." (PMID 41163811, 2025). "Our results are not in accordance with the previous studies which indicated that patients comorbid with dyslipidemia was more likely to be nonadherent to insulin therapy." (PMID 40642014, 2025). "The mechanisms behind glucocorticoid-induced dyslipidemia may include impaired LDL catabolism, increased lipoprotein lipase activity, and subsequent elevation of LDL level due to increased plasma insulin." (PMID 39759349, 2024). "Mechanistically, metabolic syndrome has been said to induce a state of chronically increased levels of FFA in the plasma, mainly due to an inability to suppress FA release from adipocytes by way of insulin insensitivity." (PMID 38247511, 2024). "Our results demonstrate an essential role for TET3 in the regulation of skeletal muscle insulin sensitivity and suggest that TET3 may be used as a potential therapeutic target for the metabolic syndrome." (PMID 38216792, 2024). "In overweight or obese BC survivors, a 16-week program of combined aerobic and resistance exercise, performed three times per week, resulted in decreased circulating insulin and IGF1 levels, increased IGFBP-3 levels, improved metabolic syndrome markers, and a 4 kg reduction in body weight." (PMID 39064705, 2024).
metabolic syndrome (continued). "In this experiment, administering PTP in C57BL/6J mice inhibited the abnormal increase in body weight, visceral obesity, and dyslipidemia induced by the HFD, and also enhanced insulin sensitivity, as shown by an insulin sensitivity test’s lower glucose levels and enhanced insulin tolerance." (PMID 39063332, 2024). "Patients with advanced fibrosis are more likely to suffer from metabolic syndrome, particularly if they have unfavorable lipid profiles, or are less sensitive to insulin compared with people without progressive fibrosis." (PMID 39161391, 2024). "Furthermore, surgical removal of VAT ameliorated metabolic syndrome while the effects of SAT removal have been inconsistent, with some demonstrating an improved or neutral effect on insulin sensitivity." (PMID 39257902, 2024). "In our study, we did not perform blood tests to assess insulin levels, dyslipidemia, and glucose homeostasis." (PMID 39457143, 2024). "By decreasing glycemia and insulin levels, OMWW-OL could have some potential beneficial effects in preventing metabolic syndrome and cancer." (PMID 39339668, 2024). "Indeed, atherogenic dyslipidemia, characterized by low HDL-C and high triglyceridemia, which represents the typical lipid phenotype observed in insulin-resistant patients." (PMID 38769519, 2024). "Progression of decrease in tissue insulin sensitivity may lead not only to T2DM but also to dyslipidemia, metabolic syndrome (MetS), or non-alcoholic fatty liver disease (NAFLD)." (PMID 38398863, 2024). "A study demonstrated that Hs treatment in rats with metabolic syndrome caused a reduction in body mass and intra-abdominal fat, as well as in triglycerides, insulin, and leptin levels in relation to the group with metabolic syndrome without treatment." (PMID 39504065, 2024). "Indeed, a meta-analysis of randomized controlled trials in metabolic syndrome subjects reinforced the short cycle of FMT efficacy to reduce glucose, insulin, and glycated hemoglobin levels and increase HDL cholesterol vs. a placebo." (PMID 39594528, 2024). "While dolphins with metabolic syndrome do not have a higher body mass index (BMI) compared to healthy controls, those with the highest insulin (i.e., greatest insulin resistance) do have a higher BMI compared to controls." (PMID 39057678, 2024). "ZSF1 obese rats displayed multiple features of metabolic syndrome at the study start age of 21–22 weeks, including elevated total cholesterol, reduced HDL cholesterol, elevated triglycerides, elevated glucose, and elevated insulin." (PMID 37805649, 2023). "The majority of patients did not use antihypertensive medications (94.9%), insulin/weight-reduction injections (97.5%), statins for dyslipidemia (98.1%), or CPAP for OSAS (99.1%)." (PMID 37593300, 2023). "It is further hypothesized that interventions that normalize/reduce activity of the insulin–IGF-I system might play a key role in the prevention and treatment of the metabolic syndrome." (PMID 36901984, 2023). "Additionally, GC increased plasma glucose, insulin, and HOMA-IR levels, confirming its potential in induce metabolic syndrome, which was consistent with previous findings." (PMID 37210385, 2023). "Fgf21 stimulates glucose uptake in adipocytes, improves insulin sensitivity and glycemic control, enhances BAT thermogenesis and ameliorates dyslipidemia, so its overexpression in L-HFD animals may represent an attempt to overcome the metabolic derangements." (PMID 36768493, 2023). "Previous data have shown that BMF may produce a significant inhibition of post-prandial insulin response in patients and that this could account for a role of BMF in maintaining a normal metabolic balance in subjects suffering from metabolic syndrome." (PMID 37629146, 2023).
metabolic syndrome (continued). "A meta-analysis of 22 RCTs indicated that WP administration significantly decreased the values of HOMA-IR, HBA1c, and fasting insulin in patients with metabolic syndrome, but did not have any impact on FBG levels." (PMID 37798798, 2023). "It is further proposed that interventions that normalize/reduce activity of the insulin–IGF-I system may play a key role in the prevention and treatment of the metabolic syndrome." (PMID 36901984, 2023). "Work in a rat model of spontaneous hypertension (exhibits hypertension, insulin resistance and dyslipidemia, features of metabolic syndrome) showed that knocking out the CFB gene improved glucose tolerance and insulin sensitivity, with redistribution of visceral to subcutaneous fat." (PMID 36377667, 2023). "Together, our findings strongly imply that apoA-IV in the 129/SvJ mice plays a very important role in regulating tissue sensitivity to insulin, the effect of which did not appear to be dependent on dyslipidemia." (PMID 38004234, 2023). "Interventions that normalize or reduce the activity of the insulin–IGF-I system might play a key role in the prevention and treatment of the metabolic syndrome and its consequences." (PMID 36901984, 2023). "Interventions that normalize/reduce activity of the insulin–IGF-I system might therefore play a key role in the prevention and treatment of the metabolic syndrome and its consequences." (PMID 36901984, 2023). "The studies that enrolled similarly aged patients with metabolic syndrome have demonstrated absence of between-group difference and only post-training improvements in insulin resistance and/or blood lipids following each training modality." (PMID 36918949, 2023). "In conclusion, the Western diet and lifestyle (Westernization), by increasing activity of the insulin–IGF-I system, may play an important etiological role in the pathogenesis of the metabolic syndrome." (PMID 36901984, 2023). "However, in other experimental settings, RAGE−/− mice exposed to an HFD were characterized by the potential of developing clusters of metabolic syndrome (MetS) manifested by accelerated weight gain, increased plasma cholesterol, and higher insulin levels compared with control animals." (PMID 37446161, 2023). "We did not, however, detect independent associations between insulin therapy during pregnancy and the later onset of AGR or dyslipidemia, as other studies have reported." (PMID 38068853, 2023). "In a metabolomics study including 5181 participants from the cross-sectional Metabolic Syndrome in Men study, the levels of KYNA and XA were shown to correlate with a decrease both in insulin secretion and insulin sensitivity as well as with an increased susceptibility to DMT2." (PMID 36766803, 2023). "Another study showed that in healthy subjects or patients with metabolic syndrome, consumption of resistant starch can increase insulin sensitivity, and in patients with T2DM, consumption of resistant starch can reduce postprandial blood sugar or insulin." (PMID 38107105, 2023). "Compared to non-DM patients, T2DM patients with and without insulin treatment had a higher prevalence of hypertension (HT) (P < 0.001) and dyslipidemia (P = 0.002)." (PMID 37542280, 2023). "We found the presence of autoantibody against glutamic acid decarboxylase, that, together with the young age at the diagnosis, the absence of metabolic syndrome and non-insulin requiring at onset, is very suggestive of latent autoimmune diabetes of adults." (PMID 36607874, 2023). "In contrast with these results, when it was tested on patients with metabolic syndrome or prediabetes, a dose of 75 mg/day did not bring significant improvements in the glycemic profile (fasting serum INS, FBS, and HbA1c)." (PMID 38003691, 2023). "Intracerebroventricular injection of insulin increases MSNA, which shows that insulin may act as a direct mediator of sympathetic overdrive in metabolic syndrome." (PMID 35204231, 2022).
metabolic syndrome (continued). "However, another study showed that a whole grain diet did not alter insulin sensitivity or the gut microbiome, even though whole grains significantly reduced energy intake and body weight and circulating markers of inflammation in adults at risk for metabolic syndrome." (PMID 36553836, 2022). "Females, patients with dyslipidemia, and those treated with lifestyle modification and insulin (with and without OHA) had higher LDL-C trends than their counterparts." (PMID 36317122, 2022). "Insulin resistance could be described as the failure response to regular circulating levels of insulin, which contributes to the pathogenesis of T2DM, hypertension, atherosclerosis, hyperlipidemia, and other metabolic syndromes." (PMID 36611967, 2022). "Patients with 25(OH)D deficiency/insufficiency were older and had significantly higher blood pressure, fasting and post-OGTT (G-AUC) glucose levels, post-OGTT insulin (I-AUC), PTH levels, and prevalence of metabolic syndrome than patients with normal serum 25(OH)D." (PMID 35057492, 2022). "When butyric acid is administered orally for 4 weeks, peripheral insulin sensitivity in healthy patients significantly improves, but glucose metabolism in patients with metabolic syndrome is not affected." (PMID 36145077, 2022). "Participants with a higher cardiometabolic risk score were likely to be older, have lower levels of physical activity, be with higher levels of BMI, WC, SBP, DBP, FPG, TG, and INS and have a higher prevalence of T2DM, hypertension, and dyslipidemia (all p < 0.05)." (PMID 36136506, 2022). "The RKFD group had a higher prevalence of metabolic syndrome and central obesity; higher levels of eGFR, eGFRcr-cys, urine albumin-creatinine ratio (UACR), fasting glucose, insulin, HOMA-IR, and FGF-23; and lower levels of total cholesterol, LDL, and serum creatinine than the group without RKFD." (PMID 36671416, 2022). "The results showed that while recipients of gut microbiota from donors with metabolic syndrome had worsened insulin sensitivity, recipients of gut microbiota from RYGB donors showed trends of improvement in insulin sensitivity, although the improvement was statistically insignificant." (PMID 36072923, 2022). "We previously have seen that insulin acutely enhances FMD in healthy middle-aged adults but not in subjects with metabolic syndrome." (PMID 34957859, 2022). "Butyrate supplementation does not increase blood butyrate levels, but it improves both peripheral and hepatic insulin sensitivity assessed by clamp studies in lean individuals without metabolic syndrome but not in individuals with metabolic syndrome." (PMID 36078124, 2022). "Next, MACCE and follow-up time were the dependent variables, while age, BMI, smoking, hypertension, dyslipidemia, SBP, DBP, FPG, HbA1c, insulin, TG, TC, HDL-C, LDL-C, sdIDL-C, ApoA-I, ApoB, Lp(a), hsCRP, neutrophils, Scr, UA, and NGAL were set as independent variables." (PMID 36397150, 2022). "In subjects with metabolic syndrome only, AI declined while PWV increased with insulin infusion." (PMID 34957859, 2022). "For example, 4 weeks of daily sodium butyrate (4 grams) supplementation only improved insulin sensitivity in lean men but not in men with metabolic syndrome." (PMID 36687671, 2022). "On the contrary, a 16-week RCT study reported that VD supplements in non-Western VDD immigrants with prediabetes failed to improve insulin sensitivity or β-cell function or change the incidence of metabolic syndrome." (PMID 36172527, 2022). "Tadalafil administration was shown to improve β-cell function in metabolic syndrome independent of insulin sensitivity." (PMID 35449082, 2022). "In addition, group B (HOMA-IR ≥ 2.5) had significantly more preoperative biomarker abnormalities (other than dyslipidemia) than group A, including leptin, ghrelin, PYY, insulin, RBP4, and LGr." (PMID 36203073, 2022).